TFF1 (trefoil factor 1)
Diseases named in the same sentence as TFF1 in open-access papers (continued):
Sharing a sentence is not in itself a finding about the gene and the disease.
tumor (continued). "Knowledge of the expression of oestrogen-responsive biomarkers could assist in treatment stratification, because tumours that express TFF3, TFF1 and progesterone receptor are more likely to respond." (PMID 25900183, 2015). "TFF3 was higher in progesterone receptor-positive tumours as compared to progesterone receptor-negative tumours (Mann–Whitney U test, P=0.001) and in TFF1-positive tumours as compared to TFF1-negative tumours (Mann–Whitney U test, P=0.000)." (PMID 25900183, 2015). "None of the other factors considered, including age, tumour size, tumour type, oestrogen receptor or TFF1, made a significant contribution to the prediction." (PMID 25900183, 2015). "The control AGS cells generated large tumor masses in nude mice, whereas the TFF1-expressing cells either failed to generate tumors or generated significantly smaller tumor as compared to control." (PMID 25015107, 2014). "In an extreme example, TFF1 expression was absent in the main tumour mass but was present in tumour cells that had infiltrated the stroma." (PMID 18722547, 2009). "The data showed that expression of TFF1 in the absence of TFIZ1 was associated with lymph node involvement (Fisher's exact; p = 0.007) and suggested that it predisposes towards tumour spread." (PMID 18722547, 2009). "Similarly in a moderately to poorly differentiated tumour, TFIZ1 expression was detected only in adjacent mucosa, whereas TFF1 was detected in almost all carcinoma cells." (PMID 18722547, 2009). "TFIZ1 expression was not detectable within the infiltrating tumour cells that express TFF1 or in any other tumour cells." (PMID 18722547, 2009). "However, the precise molecular function of TFF1 as a tumor suppressor has not been elucidated thus far." (PMID 31963721, 2020). "Analysis of TFF1 promoter methylation, and gene and protein expression in 65 ESCC patients and 88 controls revealed that TFF1 methylation levels were already increased in histologically normal tumor surrounding tissue of ESCC patients when compared to healthy esophagus of non-cancer individuals." (PMID 29296124, 2017). "Taken together, these results suggest that TFF1 may have a role as a tumor suppressor in ESCC and not in EAC, although further studies are necessary to confirm this hypothesis." (PMID 29296124, 2017). "Here, to evaluate TFF1 methylation as a potential biomarker of early ESCC diagnosis, we investigated the status of TFF1 promoter methylation and its expression in ESSC and histologically normal tumor surrounding tissue of ESCC patients in comparison to healthy esophagus of non-cancer individuals." (PMID 29296124, 2017). "However, Buache and colleagues demonstrated that TFF1 was not an oncogene in the mammary epithelium, but rather reduces the development of breast tumors and has a tumor suppressor function." (PMID 25015107, 2014). "In eight tumours, expression of TFF1 was detected in the absence of TFIZ1." (PMID 18722547, 2009). "In seven of the cases examined, neither TFIZ1 nor TFF1 were detected in the tumour cells." (PMID 18722547, 2009). "Indeed, ER+ tumours were scattered in subgroups 1 to 4 that are characterised by the over-expression of a cluster of genes, which includes CCND1, KRT19, IGF1R, LIV1, ESR1, GATA3, TFF1/pS2, ERBB4, PR and IGFBP4." (PMID 17338809, 2007). "Considering that 65 different tumor entities contained TFF1-positive cases and that the rate of positivity did not exceed 80% in any of the most frequently positive cancer entities, we do not believe that TFF1 IHC has a relevant role for the distinction of cancer entities." (PMID 39410561, 2024). "To investigate whether TFF1 is exclusively secreted by RB tumor cells and not by surrounding stromal tissue, we compared supernatants of a primary stromal cell culture and a primary RB tumor cell culture, both derived from enucleations of RB-tumor-bearing patient eyes." (PMID 37835522, 2023).
tumor (continued). "This hypothesis is supported by the fact that those three RB tumors of group III (without measurable TFF1 in AH) that do express TFF1 protein in the original tumor also secrete TFF1 in measurable amounts into the supernatant of the corresponding primary cell cultures." (PMID 35158945, 2022). "Thus, TFF1 can probably not be considered a general minimally invasive LB-based RB biomarker, but might emerge as highly beneficial for patients with a more aggressive subtype 2 RB tumor." (PMID 37835522, 2023). "Thus, TFF1 might be detectable in the aqueous humor of RB patients’ eyes, providing the opportunity to determine its expression prior to therapy without the necessity of a tumor biopsy." (PMID 35158945, 2022). "We found that TFF1 exhibited lower expression while MMP9 and CD34 showed higher expression in tumour tissues compared than in adjacent non-cancerous tissues." (PMID 30612555, 2019). "Subsequently, treatment with stERAP-6 every 4 days also significantly suppressed E2-induced expression of TFF1 and CCND1 and phosphorylation levels of Akt and MAPK in tumours, but treatment with unstapled original ERAP did not." (PMID 28500289, 2017). "Two out of three TFFs found in the human stomach (TFF1 and TFF2 but not TFF3), have been identified as tumor suppressors." (PMID 27598141, 2016). "The absence of progesterone receptor, TFF1 and especially TFF3 expression in patients with oestrogen receptor-positive tumours provides a strong indication that patients will not benefit from hormonal therapy." (PMID 25900183, 2015). "For instance for a small tumour, TFIZ1 expression was detected only in the non-involved mucosa whereas TFF1 was detected in non-involved mucosa and in both well and moderately differentiated carcinoma cells." (PMID 18722547, 2009). "In some cases, in which expression of both proteins was absent in the primary tumour, TFF1 but not TFIZ1 was expressed in infiltrating and metastatic tumour cells." (PMID 18722547, 2009). "The expression of TFF1 in the absence of TFIZ1 in infiltrating and metastatic tumour cells suggested that this pattern of expression might be associated with lymph node involvement." (PMID 18722547, 2009). "Two main groups were identified, one over-expressing markers typically found in sporadic luminal tumours such as GATA3, TFF1 and SCUBE2, and the other negative for ESR1, ERBB2 and the PR gene (PGR) (triple negative) and over-expressing genes from the basal layer such as CDH3, CRYAB and KRT5-17." (PMID 19826428, 2009). "Moreover, while TFF1-negative RB tumor cells displayed similar GIPR levels to healthy human retina, significantly increased GIPR expression levels were detected in TFF1-positive primary tumor cells, representing the subset of more advanced RBs with TFF1 as an indicating biomarker." (PMID 38730608, 2024). "Our results suggest that expression of TFF1 in the absence of the interacting protein TFIZ1 confers an invasive phenotype on tumour cells and that TFIZ1 may itself be a tumour suppressor or that it is the formation of the heterodimer that is important for the tumour suppressor activity of TFF1." (PMID 18722547, 2009).
cancer (101 papers, 2008 to 2026). A tumor composed of atypical neoplastic, often pleomorphic cells that invade other tissues. "The expression of TFF1 in cancer cells was associated with better survival rate of the patients who underwent chemotherapy, and loss of TFF1 deteriorated the benefit of gemcitabine in KPC mice." (PMID 38872370, 2024). "In several cancer types, elevated TFF1 expression has been linked to either poor or improved patient prognosis." (PMID 39410561, 2024). "Conversely, the AhR complex inhibits ESR signaling in the presence of estrogen that would otherwise normally transcribe genes such as FOS, CTSD, HSP27, and TFF1, which are over-expressed and/or mutated in various cancers." (PMID 37027342, 2023). "In several studies, enhanced levels of TFF1 were associated with the promotion of dissemination in different cancers, including those originating in the breast and GI system." (PMID 34831037, 2021). "AGR2 and TFF1, for example, are both estrogen-responsive gene elements that have been associated with a variety of different cancers." (PMID 33883548, 2021). "Since TFF1 loss has been linked to increased epithelial permeability, stemness, and cancer risk, reactivating silenced genes may provide a strategy to interrupt inflammation-driven carcinogenesis." (PMID 41573568, 2025). "Along this line, we could show that TFF1 is epigenetically regulated in RB, and others observed a correlation between cancer progression and mutations/polymorphisms in the TFF1 gene." (PMID 38730608, 2024). "Moreover, in human CRC tissue samples, we detected a loss of TFF1 in the cancer tissue, while in the adjacent normal mucosa TFF1 was detected in goblet cells of the colon." (PMID 36139637, 2022). "Moreover several studies confirm that tff1 expression is frequently lost in cancer due to deletions, mutations or methylation of the tff1 gene." (PMID 24236136, 2013). "Two of these (cancer cells and LEC1, cancer cells and LEC2) exhibited high expression of cancer cell-associated genes such as KRT19, CDH1, MUC1, and TFF1, suggesting their close interaction with cancer cells." (PMID 41249124, 2025). "For instance, in LCRC, researchers have identified a subgroup of cancer cells enriched for genes involved in maintaining of the gut lining (e.g., TFF1, TFF2, AGR3, MUC5AC)." (PMID 41450739, 2025). "The link between TFF1 expression and parameters of malignancy argues for a relevant biological role of TFF1 in cancer." (PMID 39410561, 2024). "After 14 days of incubation, the size and number were counted revealing that shTFF1 resulted in the small number of spheres significantly, also indicating that TFF1 suppress cancer stemness." (PMID 38872370, 2024). "After TFF1 overexpression in RB cells, we identified several differentially expressed genes and pathways involved in cancer progression by a gene expression array analysis." (PMID 38730608, 2024). "Anther study found STAT3 signaling, mediated by TFF1 silencing, promotes gastric inflammation-cancer transformation." (PMID 37964307, 2023). "As such, a comprehensive understanding of TFF1 as a cancer biomarker potentially changes future RB diagnostics and personalized treatment approaches, ultimately contributing to improved clinical outcomes and quality of life for affected children." (PMID 37835522, 2023). "Some of the differentially expressed genes included cancer progression factors, such as Tff1 (trefoil factor 1), Anxa10 (annexin a10), Gnai1 (G protein subunit alpha i1), Areg (amphiregulin), and Mmp7 (matrix metalloproteinase 7)." (PMID 35703180, 2022). "Although several studies manifested that TFF1 was related to different kinds of carcinoma, few studies on TFF1 in AR-positive TNBC have been reported." (PMID 36157217, 2022).
cancer (continued). "It is well-studied in relation to cancer (TFF1 OncoScore = 80) and has been proposed as a biomarker for breast and other cancers." (PMID 34007962, 2021). "Given the aforemnentioned information, loss of M2 hub ESR1 would be a driver of TFF1 downregulation in TNBC and of increased cancer aggression." (PMID 34007962, 2021). "In the present study, the expression of TFF1 was observed to gradually decreased from mucosa to deeper layers, suggesting that the loss or reduction of this protein may confer an invasive phenotype to canine gastric neoplastic cells and thus promote cancer progression." (PMID 34679875, 2021). "Additionally, there was a gradual decrease in TFF1 expression from mucosa to deeper layers, suggesting that the loss or reduction of this protein may confer an invasive phenotype on canine gastric neoplastic cells and thus promote cancer progression." (PMID 34679875, 2021). "Early-onset GC exhibited an E-cadherin-high, cyclooxygenase-2 (COX-2)-low, trefoil factor 1 (TFF1)-expressing phenotype, and COX-2 overexpression and loss of TFF1 were found in conventional cancers." (PMID 35004729, 2021). "In Elyada’s scRNA-seq analysis, ductal cancer cells in human PDAC were clustered in two major subtypes: the classic (by TFF1, TFF2, LYZ, VSIG2, and CEACAM6 marker genes) and secretory (by SPP1, CLU, CTGF, and COL18A1 marker genes) subtypes." (PMID 34035226, 2021). "Im and coworkers reported a much higher frequency of TFF1 expression in undifferentiated and diffuse type carcinomas compared with differentiated and intestinal type carcinomas." (PMID 34679875, 2021). "In the remaining eight cases, TFF1 expression was preserved (four diffuse type, three intestinal type, and one indeterminate type carcinomas)." (PMID 34679875, 2021). "For example, in gp130757F mutants, SHP2-Ras-ERK signaling is blocked, the Tff1 level is decreased, and antral adenomas and carcinomas are developed." (PMID 34066339, 2021). "TFF1, THY1, and AKR1B10 are associated with various cancers and have been implicated as biomarker candidates." (PMID 29713252, 2018). "Further genes are TFF1, known to induce metastasis and to regulate cancer-stroma interactions and S100P, which is associated with cell proliferation and survival, and is expressed in about 50% of pancreatic lesions." (PMID 29675033, 2018). "Aberrant DNA methylation was observed more frequently in EBV+ cancers than in EBV- cancers, and hypermethylation of several specific genes, such as p73 and TFF1, has also been reported." (PMID 26823082, 2016). "Most of the assayed gene regions displayed hypermethylation in cancer vs. adjacent tissue but the TFF1 and MAGEA1 regions were significantly hypomethylated (p ≤0.001)." (PMID 26510686, 2015). "We and others have demonstrated that silencing of TFF1 promotes gastric tumorigenesis and cancer development in mouse and human." (PMID 25980439, 2015). "TFF1 proteins are normally expressed in the epithelial cells of the gastric mucosa, and are abnormally expressed in gastrointestinal diseases and various cancers." (PMID 24216700, 2013). "TFF1 immunoreactivity in cancer was evaluated as -, +, ++, and +++ in 7 (43.8%), 3 (18.7%), 4 (25.0%), and 2 (12.5%), respectively." (PMID 21635755, 2011). "The striking discrepancy between TFF1 expression in only a few normal tissues and TFF1 expression in so many different cancer types demonstrates that TFF1 upregulation is a common phenomenon in cancer, which may have a significant functional role." (PMID 39410561, 2024). "Overexpression of Trefoil factor 1 is involved in pathways, including Rho-GTPases, Rho-kinase, PI3-kinase, PLC, and COX-2 and they interact with other receptor systems to activate epidermal growth factor receptor EGFR indirectly causing progression of cancer." (PMID 39839775, 2024). "Our data provide a comprehensive overview on the expression of TFF1 in human cancer." (PMID 39410561, 2024).
cancer (continued). "Additionally, a prospective biomarker like TFF1 potentially aids with early cancer detection, monitoring treatment response, and assessing disease progression, thereby improving patient outcomes." (PMID 37835522, 2023). "Monitoring TFF1 levels in RB patients’ AH and blood may not only enable early cancer detection, but also serve as a valuable indicator for therapy efficacy." (PMID 37835522, 2023). "We further observed a loss of TFF1 in cancer tissues and positive TFF1 signals in goblet cells of the normal mucosa of human CRC samples." (PMID 36139637, 2022). "A small number of hypoxia-associated genes (APLN, HIF1A, and BNIP3), cancer stem cell (CSC) markers (CD24 and CD44), hormonal regulation (HR) genes (ESR1, PGR, and TFF1), other selected genes (PPARGC1A, ILK), and HKGs (RPL32, GUSB, TBP, OAZ1 and NONO) were also included in the panel." (PMID 34206049, 2021). "An ultimate test of this hypothesis would be to check if a synthetic peptide mimicking the C-terminal CysVII of TFF1 cures Tff1KO mice from developing adenomas and carcinomas." (PMID 34066339, 2021). "Importantly, although TFF1 is predominantly expressed by cancer cells, the authors detected CCL20, CXCL1, and IL-8 in cancer cells and also in the surrounding stroma." (PMID 32373132, 2020). "Importantly, the inhibition of JAK/STAT signaling by the STAT3 inhibitor restored GATA6 expression as well as the expression of TFF1/2 in cancer cell lines." (PMID 27598141, 2016). "Similarly, overexpression of TFF1 stimulates motility or metastasis of human pancreatic stellate or carcinoma cells." (PMID 28430953, 2016). "The two promoter regions displaying cancer hypomethylation (TFF1 and MAGEA1) also displayed an inverse correlation between methylation among cancers and expression indicating that cancer-linked losses in promoter methylation were associated with increased (and abnormal) expression." (PMID 26510686, 2015). "TFF1 also had high mean methylation levels in the control mammoplasty tissue (82 %), although methylation levels were lower in adjacent tissue (72 %), and lowest in cancer tissue (49 %)." (PMID 26510686, 2015). "EAC exhibits the enhanced extracellular matrix remodeling (collagens, IGFBP7, PLAU) effects expected in an aggressive form of cancer, as well as evidence of reduced expression of genes associated with mucosal (MUC6, CA2, TFF1) and xenobiotic (AKR1C2, AKR1B10) defenses." (PMID 21829465, 2011). "Clearly, absence of TFIZ1 will affect the molecular forms of TFF1 produced and may favour production of the TFF1 dimer which stimulates cancer cell motility and invasion." (PMID 18722547, 2009). "The expression of GKN2 may suppress cancer cell proliferation through a TFF1-dependent manner." (PMID 31382983, 2019). "Through RNA‐seq analysis, we have also shown differential expression of other cancer biomarkers by CHRDL2, such as EGR1, REG4 and TFF1, which have been shown to regulate proliferation, migration and metastasis." (PMID 40434957, 2025). "TFF1, TFF2, and MUC5AC were highly expressed in foveolar cells-1 and -2, intestinal metaplasia cells, and cancer cell cluster EAC-01." (PMID 40925382, 2025). "IL-17B induces the upregulation of Chemokine Ligand 20 (CCL20), chemokine ligand 1(CXCL1), IL-8, and Trefoil Factor 1 (TFF1) chemokines via the ERK1/2 pathway, thereby facilitating cancer metastasis and enhancing viability in distant organs." (PMID 39253082, 2024). "By contrast, cluster D3, which showed an enrichment for markers such as TFF1 and S100P, was primarily composed of PDAC samples, suggesting that this subset represents cancer cells." (PMID 39485038, 2024). "Previous studies have shown that upregulation of TFF1 and TFF3 in cancer cells can facilitate EMT and confer resistance to chemotherapy and radiotherapy." (PMID 38709264, 2024). "TFF1, IGFBP7, JUNB, CLDN18 and LINC01133 genes were among the top genes of the primary cancer cells." (PMID 34055623, 2021).